PCDH1 (protocadherin 1)
Diseases named in the same sentence as PCDH1 in open-access papers (continued):
Sharing a sentence is not in itself a finding about the gene and the disease.
Arthritis (1 paper, 2024). Inflammation of a joint. "Logistic regression highlights serum PCDH1 as significant in the prediction of arthritis, and positive correlations were also found; therefore, it is possible that it is involved in the pathogenesis of musculoskeletal manifestations of the disease." (PMID 38673968, 2024). "Furthermore, a significant positive correlation was found between serum and urine PCDH1 concentrations and arthritis, respectively (τ = 0.182, p < 0.05; τ = 0.238, p = 0.001)." (PMID 38673968, 2024). "Regarding different clinical manifestations, logistic regression identified that serum concentrations of Gd-IgA1 (CI 0.943–0.992, p = 0.028), RAGE (CI 0.983–0.998, p = 0.026) and PCDH1 (CI 1.021–1.137, p = 0.012), and urinary HMGB1 (CI 1.000–1.002, p = 0.026) are predictors of arthritis in IgAV." (PMID 38673968, 2024).
breast carcinoma (1 paper, 2020). "In human breast cancer cells, transient siRNA-mediated knockdown of all three GRHL orthologs show a reduced chromatin accessibility on GRHL-regulated enhancer elements that encode proteins required for cell-cell adhesion such as protocadherin-1 (PCDH1) and serine peptidase inhibitor 1 (SPINT1)." (PMID 32974388, 2020).
hyperreactivity (1 paper, 2015). "It is likely that PCDH1, which has been identified as an airway hyperreactivity-susceptible gene, plays an important role in epithelial barrier function." (PMID 26227965, 2015).
Insulin resistance (1 paper, 2023). Increased resistance towards insulin, that is, diminished effectiveness of insulin in reducing blood glucose levels. "Therefore, we speculate that PCDH1 expression is related to insulin resistance." (PMID 37957639, 2023).
invasive carcinoma (1 paper, 2006). A carcinoma that is not confined to the epithelium, and has spread to the surrounding stroma. "For instance, expression of CDH1, a major component involved in cell–cell adhesion and frequently negatively associated with metastatic and invasive carcinomas, was enhanced in iAsIII-exposed cells, and expression of its precursor protein, protocadherin 1, was enhanced in DMAIII-exposed cells." (PMID 16507463, 2006).
lymph node metastasis (1 paper, 2022). "The HR values indicating lymph node metastasis, degree of neural invasion and PCDH1 expression with respect to the OS of the patients were 1.926, 2.09 and 1.647, respectively (P < 0.05), indicating that PCDH1 expression is an independent prognostic factor for the OS of PDAC patients." (PMID 35864095, 2022).
medulloblastoma (1 paper, 2022). A malignant, invasive embryonal neoplasm arising from the cerebellum. "PCDH1 expression decreased in medulloblastoma, giving patients poor prognosis; we found no reports of an association with BC." (PMID 37082114, 2022).
osteosarcoma (1 paper, 2023). A usually aggressive malignant bone-forming mesenchymal neoplasm, predominantly affecting adolescents and young adults. "To evaluate the effect of these EC1 residues on PCDH1’s receptor activity, we ectopically expressed EC1-‘murinized’ variants of human PCDH1 in PCDH1-knockout (KO) human osteosarcoma U2OS cells and tested their susceptibility to both, rVSVs bearing ANDV or SNV Gn/Gc, and the authentic agents." (PMID 37488123, 2023).
pulmonary disease (1 paper, 2023). "This raises the tantalizing possibility that the cellular functions of PCDH1 are intertwined with the pathogenesis of severe pulmonary disease caused by ANDV and SNV infections in humans." (PMID 37488123, 2023).
schizophrenia (1 paper, 2025). A major psychotic disorder characterized by abnormalities in the perception or expression of reality. "For instance, PTPRG (cg00974944) and PCDH1 (cg10365572), both associated with the maternal schizophrenia PGS, are involved in cell growth regulation and neural adhesion, respectively, supporting the role of dysregulated synaptic processes in schizophrenia risk." (PMID 40181191, 2025).
tumor (10 papers, 2019 to 2026). "The results showed that PCDH1 expression was significantly associated with the depth of tumour invasion (P = 0.023) and lymph node metastasis (P = 0.015)." (PMID 35864095, 2022). "Since IL-6, which is a widely studied NF-κB effector, is closely related to tumour progression, we sought to determine whether its expression level was associated with PCDH1 in PDAC tissues." (PMID 35864095, 2022). "To assess the impact of PCDH1 on tumor cell motility, we performed both Transwell migration and wound-healing assays in BxPC3 and SW1990 cells." (PMID 41602375, 2026). "Collectively, these data demonstrate that PCDH1 exerts its oncogenic role in PDAC at least partly by modulating PI3K-Akt signaling and associated tumor-promoting effectors." (PMID 41602375, 2026). "Here, we systematically interrogated transcriptomic datasets, validated expression patterns in patient specimens, and functionally characterized PCDH1 in PDAC models to determine its contribution to tumor progression and stemness regulation." (PMID 41602375, 2026). "This dual role—sustaining CSC traits while dampening anti-tumor immunity—renders PCDH1 an especially compelling therapeutic candidate." (PMID 41602375, 2026). "Immunohistochemistry of paired tumor and adjacent tissues from six patients further demonstrated pronounced membranous PCDH1 staining in PDAC specimens compared with paracancerous counterparts." (PMID 41602375, 2026). "Both BxPC3 and SW1990 cells with PCDH1 silencing generated significantly smaller and fewer tumor spheres compared with controls, with differences becoming pronounced by day 5 of culture." (PMID 41602375, 2026). "Beyond tumor-intrinsic functions, PCDH1 expression exhibited strong correlations with an immunosuppressive tumor microenvironment." (PMID 41602375, 2026). "This analysis revealed associations with multiple proteins, including SMAD3, RNF14, PPM1A, and OPHN1, implicating PCDH1 in signaling cascades relevant to tumor progression and stemness regulation." (PMID 41602375, 2026). "Taken together, these findings position PCDH1 at the intersection of stemness regulation, tumor aggressiveness, and treatment resistance in PDAC." (PMID 41602375, 2026). "To further elucidate the immunological role of PCDH1 in PDAC, we evaluated its association with tumor immune infiltration using ESTIMATE and CIBERSORT algorithms." (PMID 41602375, 2026). "PCDH1+ tumor cells harbored the RHOB, C5AR2, HAPLN3, SERPINE2, ELN, EPS8L2, and ITGA5 genes, associated with cell migration and metastasis." (PMID 39685635, 2024). "The expression of PCDH1 in cells obtained from primary tumours or metastatic biopsies was identified using single-cell RNA sequencing (scRNA-seq)." (PMID 37957639, 2023). "We demonstrated that PCDH1 expression was upregulated in PDAC tissues, and its expression levels were associated with the depth of tumour invasion and lymph node metastasis." (PMID 35864095, 2022). "The results showed that the volume of the tumours generated from PCDH1-silenced Panc-1 and BxPC-3 cells was dramatically smaller than that of the control groups." (PMID 35864095, 2022). "The results showed that PCDH1 was localized to the cytoplasm and cytomembrane and that its expression was significantly higher in the tumour tissues than in the normal tissues." (PMID 35864095, 2022). "A high level of PCDH1 expression indicated the presence of extensive tumour cell infiltration and lymph node metastasis." (PMID 35864095, 2022). "Further experiments demonstrated that PCDH1 was frequently expressed in PDAC cell lines and tissues, and its expression level was associated with the depth of tumour invasion and lymph node metastasis." (PMID 35864095, 2022). "PCDH1 displayed broader localization, being highly expressed in malignant cells as well as fibroblasts, endothelial cells, and select immune subsets, consistent with a role in mediating tumor–stroma interactions." (PMID 41602375, 2026).
tumor (continued). "Notably, genes implicated in oncogenic signaling and tumor progression, including GNB4, EGF, MYB, IL6R, ANGPT4, and ITGB8, were consistently downregulated in both BxPC3 and SW1990 cells following PCDH1 silencing." (PMID 41602375, 2026). "We found that the abundance of PCDH1 mRNA was higher in the GEO tumour tissues." (PMID 35864095, 2022). "Moreover, we assessed microarray data from the Gene Expression Omnibus (GEO) GSE62452 dataset to compare the expression of PCDH1 in tumour and normal tissues." (PMID 35864095, 2022). "Disruption of this gene by autoreactivity, possibly through the lncRNA neighbor to PCDH1, may alter the response to environmental antigens that modulate tumor-immune interactions in BC." (PMID 37082114, 2022). "Together, these findings provide functional evidence that PCDH1 promotes the migratory phenotype of PDAC cells, supporting its role in driving tumor invasiveness." (PMID 41602375, 2026). "Protocadherin 1 (PCDH1), which binds to SMAD3 and acts as a tumor suppressor, was significantly upregulated (p < 0.0001 vs. ctrl)." (PMID 39054369, 2024). "Immunohistochemistry (IHC) staining of PCDH1 in 197 histopathologically confirmed PDAC tissues was performed, and the histochemistry score (H score) was determined for each tumour tissue and adjacent normal pancreatic tissue (4 degrees)." (PMID 35864095, 2022). "The expression levels of five genes (ADAM28, BTBD6, CXCL5, PCDH1, and LOC102724689) comprise three rules for the identification of pancreatic-tissue-derived PDX tumor tissues." (PMID 31456818, 2019). "Therefore, our results provide evidence showing that high PCDH1 expression in PDAC promotes acquisition of the SP phenotype, an inherent stem cell characteristic correlated with tumour growth, invasion and metastasis." (PMID 35864095, 2022). "In more detail, SIGLEC17P expression could be used by Tregs to circulate among all tissues; CD33, PCDH1, JAM2, CDHR3, and ITGA3 would orchestrate migration/retention in NI TDLNs; CADM1 in I TDLNS; and CEACAM6 in tumor." (PMID 32601304, 2020).
infection (8 papers, 2019 to 2025). The state of being infected such as from the introduction of a foreign agent such as serum, vaccine, antigenic substance or organism. "By contrast, loss of protocadherin-1, a recently identified entry receptor for some hantaviruses, substantially reduced hantavirus entry and infection." (PMID 34232859, 2021). ") were largely protected against a lethal outcome of ANDV challenge while the control animals carrying WT PCDH1 succumbed to infection." (PMID 37488123, 2023). "Together, these findings indicate that the F83L mutation abolishes PCDH1 binding to SNV Gn/Gc, explaining the resistance of MLMECs to SNV entry and infection and the enhancing effect of human PCDH1 expression in these cells." (PMID 37488123, 2023). "By contrast, and consistent with the higher affinity of the ANDV Gn/Gc:PCDH1 interaction, a combination of both mutations was necessary to reduce ANDV Gn/Gc-mediated infection." (PMID 37488123, 2023). "We previously demonstrated that ANDV infection and virulence was highly attenuated in Syrian hamsters engineered to lack PCDH1 expression." (PMID 37488123, 2023). "To further examine the effect of PCDH1 dimerization on its hantavirus receptor activity, we stably expressed PCDH1 lacking the EC4 domain in PCDH1-KO U2OS cells and tested their susceptibility to Gn/Gc-mediated infection." (PMID 37488123, 2023). "However, a recent study has shown that protocadherin-1 is crucial for infection of endothelial cells by the pathogenic New World orthohantaviruses, Andes virus (ANDV) and Sin Nombre virus (SNV), and suggests that integrins probably only play minor roles in cellular infection." (PMID 36223391, 2022). "PCDH1 was identified in a comprehensive genetic screen for ANDV entry factors, and its genetic depletion in endothelial cells inhibited viral entry and infection." (PMID 34232859, 2021). "We found, instead, that ectopic expression of human PCDH1 in MLMECs enhanced infection of rVSV-SNV-Gn/Gc, indicating that a molecular incompatibility between SNV Gn/Gc and murine PCDH1 is at least partially responsible for the entry block in murine endothelial cells." (PMID 37488123, 2023). "Although all the PCDH1 variants expressed well and localized to the cell surface, only the F83L substitution failed to restore cellular susceptibility to SNV entry and infection, suggesting F83L is determinative." (PMID 37488123, 2023). "Similar results were obtained in a third assay in which viral particles were pre-incubated with sEC1-2 in solution as above, and then exposed to PCDH1-bearing target cells: both sEC1-2(WT) and sEC1-2(F83L) could block rVSV-ANDV-Gn/Gc infection, but the latter was less active." (PMID 37488123, 2023). "Moreover, over-expression of human PCDH1 bearing F83L failed to enhance rVSV-SNV-Gn/Gc infection in MLMECs, supporting the conclusion that the human-murine sequence difference at PCDH1 position 83 renders murine endothelial cells less susceptible to SNV Gn/Gc-dependent entry." (PMID 37488123, 2023).
cancer (7 papers, 2021 to 2026). A tumor composed of atypical neoplastic, often pleomorphic cells that invade other tissues. "Integrative analyses revealed that PCDH1 is markedly upregulated in tumors, correlates with poor patient survival, and drives malignant phenotypes including proliferation, migration, and cancer stem cell maintenance." (PMID 41602375, 2026). "We identified four samples with alterations in PCDH1 from the mutation and CNA data of 175 patients (PAAD, TCGA, and Pan-Cancer Atlas)." (PMID 37957639, 2023). "The Cancer Genome Atlas and Genotype-Tissue Expression databases were used to identify the expression and prognostic model of protocadherin 1 (PCDH1)." (PMID 37957639, 2023). "To determine whether PCDH1 contributes to cancer stemness in PDAC, we examined its effect on canonical stemness markers and sphere-forming capacity." (PMID 41602375, 2026). "Based on the acquired data, it is speculated that the high PCDH1 expression affects the transforming growth factor-beta (TGF-β) signalling pathway, which is closely associated with tumourigenesis and cancer regulation." (PMID 37957639, 2023). "PCDH1 was differentially expressed in almost all TCGA cancer types." (PMID 37957639, 2023). "First, we studied PCDH1 expression in pan-cancer samples and, compared them with normal samples through data mining using The Cancer Genome Atlas (TCGA) database, and identified the up-regulation of PCDH1 in patients with PAAD." (PMID 37957639, 2023). "In summary, the TCGA pan-cancer data suggests that PCDH1 is highly expressed in PAAD." (PMID 37957639, 2023). "In addition, NF-κB downstream effectors, such as CCND1, CCNE2, MET, VEGFA, CD44 and CD133, contribute to cancer proliferation, metastasis and stemness, and their expression is regulated by PCDH1." (PMID 35864095, 2022). "Nevertheless, the function of PCDH1 in cancers has rarely been reported." (PMID 35864095, 2022). "Also, several genes of cancer suppressors were activated after mitochondrial administration, including Csad, Ccdc30, Macrod1, Pcdh1, Tprkb, and Hdac11." (PMID 34131403, 2021). "High levels of PCDH1 expression correlated with poor prognosis of OS in PAAD and other cancers, including KIRP." (PMID 37957639, 2023).
respiratory diseases (2 papers, 2019 to 2023). "Overall, these results reveal the molecular mechanism underlying adhesiveness of PCDH1 and δ1-protocadherins, also shedding light on PCDH1’s role in maintaining airway epithelial integrity, the loss of which causes respiratory diseases." (PMID 31583286, 2019). "Protocadherin-1 (PCDH1) is a non-clustered δ1 protocadherin involved in respiratory diseases." (PMID 31583286, 2019).
genetic diseases (1 paper, 2023). "Although PCDH1 has not been reported to be involved in genetic diseases so far, other members of the protocadherin gene family have been reported to be expressed in developing muscles and tendons." (PMID 37761858, 2023).
nervous system disorder (1 paper, 2024). A non-neoplastic or neoplastic disorder that affects the brain, spinal cord, or peripheral nerves. "In light of the expression and function of PCDH1 as well as its association with nervous system disorders in humans, the variant in bovine PCDH1 may be the cause of SS in one case." (PMID 39732776, 2024).
PCDH1 also shares sentences with these, for which no sentence is quoted: viral infection (2 papers); allergic asthma (1); Allergy (1); atopic dermatitis (1); autosomal recessive disease (1); breast invasive carcinoma (1); cervical tumors (1); cholangiocarcinoma (1); eczema (1); gynecologic cancers (1); ischemic cardiomyopathy (1); kidney chromophobe (1); lung adenocarcinoma (1); lung carcinoma (1); melanoma (1); nephritis (1); pancreatic adenocarcinoma (1); paraganglioma (1); pheochromocytoma (1); prostate adenocarcinoma (1); thyroid carcinoma (1); vasculitis (1).